PURG (purine rich element binding protein G)
Synonyms: PURG-A; PURG-B; PURGA; PURGB
Tractability: Antibody: the Human Protein Atlas places it where antibodies can reach. PROTAC: ubiquitination databases record sites on it; its protein half-life has been measured.
Gene: Protein-coding gene on chromosome 8 (30,995,802 to 31,033,715, reverse strand). Ensembl gene ENSG00000172733.
Subcellular location: Nucleus
Subcellular location (Human Protein Atlas): Nucleoplasm; Basal body; Centrosome; Cytokinetic bridge; Nucleoli; Plasma membrane
Gene Ontology:
Molecular function: RNA binding; DNA-binding transcription factor activity, RNA polymerase II-specific; purine-rich negative regulatory element binding; RNA polymerase II transcription regulatory region sequence-specific DNA binding
Biological process: regulation of transcription by RNA polymerase II
Cellular component: nucleus
Genetic constraint (gnomAD): Loss-of-function variants: 3 observed, 23.89 expected, observed/expected ratio (o/e) 0.13, 90% interval 0.056 to 0.32. The upper end of that interval is the gene's LOEUF score, 0.32, which puts it in group 1 of 6, group 1 being the genes least tolerant of losing a copy. Missense variants: 371 observed, 447 expected, observed/expected ratio (o/e) 0.83, 90% interval 0.76 to 0.9. Synonymous variants: 180 observed, 175.17 expected, observed/expected ratio (o/e) 1.03, 90% interval 0.91 to 1.16.
Homologues: Orthologues: guinea pig PURG (98% identical), pig PURG (98% identical), mouse Purg (97% identical), rabbit PURG (86% identical), chimpanzee PURG (86% identical), macaque PURG (86% identical), rat Purg (83% identical), dog PURG (81% identical), zebrafish purg (59% identical), Drosophila melanogaster Pur-alpha (33% identical), Caenorhabditis elegans plp-1 (23% identical), Caenorhabditis elegans plp-2 (15% identical). Paralogues in human: PURB (49% identical), PURA (48% identical).
Diseases named in the same sentence as PURG in open-access papers:
PURG is named in the same sentence as 2 diseases in open-access papers, as found by Europe PMC text mining. Sharing a sentence is not in itself a finding about the gene and the disease.
PURG shares sentences with these, for which no sentence is quoted: breast carcinoma (1 paper); cognitive decline (1).